VWF (von Willebrand factor)
Diseases named in the same sentence as VWF in open-access papers (continued):
Sharing a sentence is not in itself a finding about the gene and the disease.
COVID-19 (continued). "The upregulation of the integrins GPIIb (CD41) and GPIIIa (CD61) and the von Willebrand factor (VWF) receptor subunits, GPIbα and GPIX, known to regulate platelet–leukocyte interactions, together with P-selectin may contribute to exacerbate the inflammatory response in COVID-19 patients." (PMID 34948438, 2021). "The authors state “COVID-19 is associated with a substantial increase in von Willebrand factor levels, which can exceed the ADAMTS13 processing capacity resulting in the formation of large von Willebrand factor multimers indistinguishable from thrombotic thrombocytopenic purpura”." (PMID 34208470, 2021). "Although the prognostic and treatment implications of APS antibodies and greatly elevated VWF in COVID-19 remain unknown and IgM antibodies are usually not pathogenetic in APS, the authors argued that such unusual laboratory profile suggests a possible role for therapeutic-dose anticoagulation." (PMID 32552865, 2020). "In a single-center cross-sectional study as reported by Ali and Spinler, levels of vWF antigen and activity were found to be three times higher in non-intensive care unit (ICU) COVID-19 patients compared to a control group." (PMID 41311551, 2025). "Overall, our findings indicate that COVID-19-related coagulopathy does not fulfill the criteria for classical TMA but shows features of complement-mediated endothelial injury and vWF dysregulation." (PMID 40508203, 2025). "It has been shown that activation of vWF secretion and suppression of thrombomodulin and EPCR expression in the endothelium in COVID-19 do not require cell contact with viral particles." (PMID 39457048, 2024). "We provide representative gel analyses of patients with COVID-19 having increased VWF concentrations and antibodies to ADAMTS13, critically ill patients without COVID-19 and patients with acute TTP." (PMID 37380654, 2023). "It is rather interesting to mention that a recent study led to the conclusion that vWF antigen and activity were three times higher in non-intensive care unit (ICU) COVID-19 patients, compared to both the control group and ICU patients." (PMID 36295093, 2022). "VWF and ATDAMTS13 levels ad activity reported in critically ill COVID-19 patients with and without preexisting comorbidities." (PMID 34575297, 2021). "In this study, we were able to demonstrate that in critically ill COVID-19 patients, circulating P-selectin, E-selectin, Ang-2, ICAM-1, and vWf levels on ICU admission are elevated in non-survivors compared to survivors." (PMID 33477776, 2021). "VWF, ADAMTS13, thrombin generation, and plasmin generation characteristics by survivors and non–survivors in COVID-19 positive and negative groups." (PMID 35087853, 2021). "Ang2 was significantly higher in ICU patients with COVID-19 requiring IMV compared to those who did not, as was thrombomodulin and vWF:Ag." (PMID 34446527, 2021). "Nonetheless, this does not diminish the potential relevance of VWF/ADAMTS13 axis parameters, and of plasma thrombin and plasmin generation parameters, regarding the COVID-19 (+) patients evaluated in this study." (PMID 35087853, 2021). "The other major clotting factor, vWF antigen was shown to be increased (mean 565%, SD 199) in ICU and (278%, SD 133) non-ICU COVID-19 patients." (PMID 33193350, 2020). "Although they did not review the role of VWF in mortality, we confirmed that VWF, BDCA3, and uPA play important roles in systemic inflammation and severity, which can lead to increased mortality in COVID-19 patients." (PMID 38965511, 2024). "Although many reports have demonstrated decreased ADAMTS13 activity and increased von Willebrand factor (VWF) in patients with COVID-19, ADAMTS-13 activity was not less than 10% in COVID-19 and the clinical usefulness of a mild decrease in ADAMTS-13 is not clear." (PMID 37175680, 2023).
COVID-19 (continued). "Our observations indicate that VWF, possibly perpetuated by (local) relative lack of ADAMTS13 activity, might play a critical role in the pathomechanism of COVID-19 being more than a marker of endothelial damage." (PMID 37333991, 2023). "However, also in non-COVID-19 patients 100% of ICU-admitted and 77% in non-ICU patients were characterized by elevated vWF." (PMID 33564744, 2021). "However, unlike in TTP the present data did not reveal thrombocytopenia in conjunction with increased VWF:AG levels and CBA in COVID-19 (+) patients." (PMID 35087853, 2021). "The VWF/ADAMTS13 axis is significantly imbalanced in favor of higher VWF levels and activity and lower ADAMTS13 levels and activity in both acutely ill COVID-19 (−) and COVID-19 (+) non-survivors at the time of hospital admission." (PMID 35087853, 2021). "However, to our knowledge, no study has specifically focused on VWF/ADAMTS13 axis changes of coagulation combined with thrombin and plasmin generation in COVID-19 (−) or COVID-19 (+) patient cohorts at the time of hospital presentation and admission." (PMID 35087853, 2021). "Our results demonstrate that COVID-19 driven cytotoxicity is cell selective not resulting in impaired endothelial cell viability but resulting in cellular activation and upregulation of ICAM-1 with subsequent immune cell adhesion and vWF deposition in the extracellular matrix." (PMID 38041432, 2024). "A study of 88 PCR-proven COVID-19 patients demonstrated that COVID-19 non-survivors had significantly lower levels of ADAMTS-13 activity (32.2 iu/dL vs. 50.6 iu/dL, p = 0.035) and higher levels of vWF (395.5 iu/dL vs. 295.5 iu/dL, p = 0.033) when compared to patients who survived." (PMID 39274365, 2024). "In addition to VWF/ADAMTS13 axis dysregulation, plasma predictors of thrombosis and fibrinolysis potential, such as thrombin and plasmin generation, respectively, have not been well-defined in COVID-19 patients." (PMID 35087853, 2021).
Von Willebrand disease (308 papers, 2007 to 2026). von Willebrand disease (VWD) is a hereditary bleeding disorder caused by a genetic anomaly leading to quantitative, structural or functional abnormalities of the Willebrand factor (von Willebrand factor; VWF). "Decreased or functionally defective VWF results in von Willebrand disease (VWD), whereas high VWF levels have been associated with thrombotic risk." (PMID 41743270, 2026). "Von Willebrand disease (vWD) is a bleeding disorder with autosomal-dominant inheritance caused by quantitative and qualitative abnormalities in von Willebrand factor (vWF), which plays a role in primary hemostasis." (PMID 42137686, 2026). "The patient was found to have type 2 von Willebrand disease, an autosomal dominant variant characterised by defective von Willebrand factor, translating into a moderate to severe bleeding risk." (PMID 40842737, 2025). "Von Willebrand disease (vWD) is a common inherited bleeding disorder caused by a deficiency of von Willebrand factor (vWF), a glycoprotein involved in hemostasis." (PMID 40995259, 2025). "von Willebrand disease (VWD) is the most common inherited bleeding disorder caused by quantitative or qualitative defects in VWF." (PMID 41322113, 2025). "Von Willebrand disease is a rare inherited bleeding disorder characterized by deficient or defective von Willebrand factor, crucial for platelet adhesion and aggregation." (PMID 40621141, 2025). "von Willebrand disease (vWD) is a common disorder among hemophiliacs and is caused by an insufficient amount of or the abnormal function of von Willebrand factor (vWF) in plasma." (PMID 40277561, 2025). "Type 2A von Willebrand disease (VWD) is characterized by impaired platelet adhesion due to the selective loss of high-molecular-weight von Willebrand factor (VWF) multimers." (PMID 41322113, 2025). "Mutations in VWF result in deficiencies in the VWF protein predisposing mild to severe bleeding, a disorder known as Von Willebrand disease (vWD)." (PMID 40362344, 2025). "In type 2B von Willebrand disease, the mutations in the A1 domain resulted in vWF inappropriate binding to platelet GPIBα with elongated bond lifetimes." (PMID 40277561, 2025). "Von Willebrand Disease is the most prevalent inherited bleeding disorder (reported incidence 0.6–1.3%), characterised by a deficiency or dysfunction of vWF, a key protein in platelet adhesion." (PMID 40572775, 2025). "Another disorder influencing hemodynamic stability during pregnancy is von Willebrand disease (vWD), a bleeding disorder resulting from deficiency in von Willebrand Factor (vWF), which normally functions to promote platelet adhesion." (PMID 40981115, 2025). "von Willebrand disease (VWD) type 2 arises from variants in von Willebrand factor (VWF) that disrupt its essential hemostatic functions." (PMID 40393667, 2025). "Von Willebrand disease (VWD) is a hereditary coagulopathy caused by a genetic deficiency in von Willebrand factor (VWF), a plasma glycoprotein." (PMID 40616878, 2025). "The clinical importance of VWF is highlighted by von Willebrand disease (VWD), which is generally caused by mutations in the VWF gene and is characterized by a bleeding phenotype, which can vary in severity from asymptomatic to life-threatening bleeding." (PMID 40687385, 2025). "Mutations in the VWF gene, leading to the inherited bleeding disorder von Willebrand disease (VWD), lead to abnormal WPBs formation due to an impairment of VWF maturation." (PMID 40387003, 2025). "Deleterious mutations in the F8 gene result in the X-linked bleeding disorder hemophilia A, whereas mutations in the VWF gene that result in deficient or dysfunctional VWF in the plasma lead to the bleeding disorder von Willebrand disease (VWD)." (PMID 40488174, 2025). "Elevated plasma VWF levels have been associated with an increased atherothrombosis risk, while von Willebrand disease, characterized by low or defective VWF, is associated with a decreased risk of developing atherothrombosis." (PMID 40093962, 2025).
Von Willebrand disease (continued). "Type 1 von Willebrand disease (VWD) is caused by a partial quantitative reduction in plasma von Willebrand factor (VWF) levels and accounts for approximately 75% of VWD cases." (PMID 39265913, 2024). "Von Willebrand disease (VWD) is a bleeding disorder caused by quantitative or qualitative defects of von Willebrand factor (VWF), an adhesive protein that binds platelets to the sub-endothelium and carries factor VIII." (PMID 39442071, 2024). "Secondly, Von Willebrand disease is an inherited bleeding disorder due to a deficiency of the Von Willebrand factor." (PMID 39478767, 2024). "Although a congenital abnormality of vWF causes a hemostatic disorder that is recognized as von Willebrand disease, various conditions induce an acquired abnormality of vWF activity, known as acquired von Willebrand syndrome." (PMID 38822325, 2024). "The prevalent coagulation factor deficiencies manifest in three main conditions: Hemophilia A (Factor VIII deficiency), Hemophilia B (Factor IX deficiency), and von Willebrand disease (deficient or defective plasma von Willebrand Factor)." (PMID 39545083, 2024). "Von Willebrand disease (VWD) is a hemostatic disorder characterized by a quantitative or qualitative deficiency of the Von Willebrand factor (VWF)." (PMID 38435184, 2024). "Deficiency of vWF leads to von Willebrand disease, the most common bleeding disorder that causes delays in clot formation." (PMID 39545083, 2024). "Von Willebrand’s disease (vWD) is the most common heritable bleeding disorder in dogs and is caused by a deficiency in von Willebrand’s Factor (vWF)." (PMID 39834923, 2024). "A deficiency or dysfunction of vWF can lead to von Willebrand disease, a bleeding disorder characterized by prolonged bleeding time and impaired platelet function." (PMID 38649864, 2024). "Type 2B von Willebrand disease (vWD) is caused by mutations in the von Willebrand factor gene, which causes significant interaction between von Willebrand Factor and platelets, thus increasing aggregation and leading to thrombocytopenia." (PMID 39128726, 2024). "Von Willebrand Disease (VWD) is an inherited bleeding disorder caused by a deficiency or dysfunction of von Willebrand factor (VWF), a protein that is essential for blood clotting." (PMID 37241186, 2023). "Low levels of VWF can lead to a bleeding tendency, such as in von Willebrand disease, and elevated levels of VWF are associated with an increased risk for thrombosis and cardiovascular disease." (PMID 37998383, 2023). "VWF deficiency can lead to von Willebrand disease (VWD), and VWF overactivition can lead to thrombotic thrombocytopenic purpura (TTP)." (PMID 36944974, 2023). "One patient had pathogenic variants in the vWF gene, so his diagnosis was changed from HA to von Willebrand disease (vWD) type 2N." (PMID 36833187, 2023). "Von Willebrand disease (VWD) is a common bleeding disorder caused by mutations in the von Willebrand factor gene (VWF)." (PMID 37845247, 2023). "AVWFD is a condition in which VWF levels are reduced as a result of an underlying medical condition, such as shear stress-induced von Willebrand disease (SS-VWD)." (PMID 37241186, 2023). "Because VWF is essential for normal hemostasis, a deficiency or dysfunction of VWF leads to the common bleeding disorder, von Willebrand disease (VWD)." (PMID 37845247, 2023). "von Willebrand disease (VWD) is an inherited hemorrhagic disease caused by von Willebrand factor (VWF) gene mutation." (PMID 37240845, 2023). "A deficiency or defect in vWF leads to a number of blood and bleeding disorders, the most common being the inherited von Willebrand disease." (PMID 35612303, 2022). "Background von Willebrand disease (VWD) is a genetic bleeding disorder caused by defects of von Willebrand factor (VWF), quantitative (type 1 and 3) or qualitative (type 2)." (PMID 36299619, 2022). "Von Willebrand disease is an inherited hemorrhagic disorder generally caused by an autosomal dominant plasma vWF deficiency." (PMID 35343091, 2022).
Von Willebrand disease (continued). "Von Willebrand disease (VWD) is a bleeding disorder caused by quantitative (type 1 or 3) or qualitative (type 2A/2B/2M/2N) defects of circulating von Willebrand factor (VWF)." (PMID 36165954, 2022). "Von Willebrand disease (VWD) is the most frequent autosomally inherited bleeding disorder caused by quantitative deficiency or qualitative changes in the von Willebrand factor (VWF) protein structure." (PMID 35505650, 2022). "Von Willebrand disease (vWD) is the most common inherited bleeding disorder caused by mutations within the von Willebrand factor (vWF) gene." (PMID 35210927, 2022). "Reduced VWF antigen levels or reduced functionality of VWF results in a bleeding phenotype, with congenital defects or deficiencies leading to von Willebrand disease (VWD), the most common inherited bleeding disorder." (PMID 35327035, 2022). "Von Willebrand disease (VWD) is an autosomal inherited hemostasis disorder caused by a deficiency or defect in the blood protein known as von Willebrand factor, which is necessary for platelets to adhere to damaged vessel walls." (PMID 36324358, 2022). "von Willebrand’s disease (vWD) is an autosomal (dominant or recessive) hemorrhagic coagulopathy characterized by a deficiency of vWF." (PMID 35955419, 2022). "Another SNP, rs41276738 (VWF R854Q) linked to type 2 N von Willebrand disease, reached at 1% AAF only in the AMR population." (PMID 35337356, 2022). "von Willebrand disease (vWD) is an inherited bleeding disorder that is caused by a defect of von Willebrand factor (VWF), a glycoprotein important for platelet adhesion to the subendothelium after vascular injury." (PMID 35741733, 2022). "Deficient VWF leads to von Willebrand disease (VWD), the most recurrent inherited bleeding disorder, which is mainly characterized by mucocutaneous bleeding and bleeding from an injury or after a surgery." (PMID 35328514, 2022). "VWF is of great importance in the hemostasis, which can be illustrated by the fact that its deficiency and/or abnormality causes von Willebrand disease (VWD), the most frequent inherited human bleeding disorder." (PMID 35498136, 2022). "The von Willebrand disease is caused by a quantitative a quantitative (reduction of VWF antigen) or qualitative (reduction of VWF activity) defect of VWF and is also characterized by bleeding symptoms." (PMID 34014399, 2022). "Von Willebrand disease is one of the most common inherited bleeding disorders, caused by any one of hundreds of mutations in the VWF gene." (PMID 34948044, 2021). "von Willebrand disease (vWD) is a common, inherited, genetically and clinically heterogeneous hemorrhagic disorder caused by a deficiency or dysfunction of the protein von Willebrand factor (vWF)." (PMID 34394804, 2021). "We believe that our findings will facilitate further understanding of the pathology associated with VWF, such as von Willebrand disease, as well as the mechanism of membrane fission." (PMID 34904569, 2021). "A silent heterozygous substitution c.7464C>T in exon 44 of the von Willebrand factor (VWF) gene causes type 1 von Willebrand disease." (PMID 32951567, 2021). "A deficiency of VWF is associated with a congenital bleeding disorder called von Willebrand disease (VWD)." (PMID 34564132, 2021). "There are three types of Von Willebrand disease: type 1 is a deficiency in vWF, type 2 results from functional losses or gains of vWF and can be further complicated with a quantitative deficiency, and type 3 is when there is no vWF present at all." (PMID 34501395, 2021). "A translationally silent single nucleotide mutation in exon 44 (E44) of the von Willebrand factor (VWF) gene is associated with inefficient removal of intron 44 in a von Willebrand disease (VWD) patient." (PMID 34948044, 2021). "Deficiencies of VWF, either quantitative or qualitative, are associated with the most common inherited bleeding disorder known as Von Willebrand disease (VWD)." (PMID 34575297, 2021).